APOBEC3B (apolipoprotein B mRNA editing enzyme catalytic subunit 3B)
Diseases named in the same sentence as APOBEC3B in open-access papers (continued):
Sharing a sentence is not in itself a finding about the gene and the disease.
bladder cancer (16 papers, 2017 to 2025). "The APOBEC3A and APOBEC3B cytosine deaminases are the main mutators of bladder cancer genomes (evidenced as COSMIC SBS2 and SBS13 mutational signatures in 93% of bladder tumours) and therefore account for most of the neoantigen load in bladder tumours." (PMID 36358715, 2022). "Expression of two enzymes of the family APOBEC3A and APOBEC3B is associated with high TMB in bladder carcinomas." (PMID 35323317, 2022). "With respect to tumor mutation burden, APOBEC3B expression is strongly correlated with the total mutation burden in bladder cancer (r = 0.3308, p < 0.001)." (PMID 33925044, 2021). "A high expression of APOBEC3B was observed in 71 of the 94 patients (75.5%), similar to the TCGA bladder cancer cohort data for APOBEC-mediated mutation enrichment scores (83.5%)." (PMID 33925044, 2021). "Expression of APOBEC3A and APOBEC3B were the only APOBEC enzymes that directly correlate with the total mutation burden in bladder cancer." (PMID 29435122, 2018). "Several studies have found that E6 can directly participate in the transcriptional upregulation of APOBEC3B and contribute to APOBEC3B mutation signature, which is widely found in a variety of tumors, including cervical cancer, head and neck squamous cell carcinoma, bladder cancer, and lung cancer." (PMID 35903294, 2022). "These distinct mutational characteristics suggest that the tumor biology of bladder cancer may be different between those with high and low expression of APOBEC3B and that the APOBEC3B activity may be associated with DNA damage response." (PMID 33925044, 2021). "Another study has also shown that bladder cancer with high APOBEC3B expression has a better prognosis compared to those with low expression, and higher infiltration of various immune cells and expression of immune checkpoints, including CD276." (PMID 38827321, 2024). "For example, the single-nucleotide polymorphism (SNP) rs1014971—which is located upstream of the APOBEC3 gene cluster—is associated with increased APOBEC3B expression, enrichment of APOBEC3-induced mutations, and higher bladder cancer risk." (PMID 36978147, 2023). "In particular the SNP rs1014971 has been linked to increased APOBEC3B expression and enrichment of APOBEC‐related mutational signatures in bladder cancer." (PMID 36394079, 2023). "Previous studies have indicated that APOBEC3B is uniquely enriched in cervical, breast, lung, and bladder cancers." (PMID 36203448, 2022). "An analysis of a bladder cancer cohort in The Cancer Genome Atlas (TCGA) database revealed that the expression of APOBEC3B, which is one of several members of the APOBEC family, is upregulated and is associated with patient survival." (PMID 33925044, 2021). "Higher expression of the mutagenic APOBEC3B isoform predicted shorter progression-free survival in bladder cancer patients." (PMID 33753867, 2021). "APOBEC3B presented the strongest correlation (Spearman = 0.30, p < 0.001), and the expression level of APOBEC3B mRNA in bladder cancer was significantly higher than the median value of all samples of 14 cancer types evaluated in a previous study." (PMID 33925044, 2021). "Many earlier studies reported elevated expression and activity of APOBEC3B and APOBEC3A in bladder cancer and of APOBEC3B in head and neck cancer patients." (PMID 29642934, 2018). "APOBEC mutagenesis is associated with increased expression of immune signatures, including interferon signaling, and expression of APOBEC3B is increased after stimulation of APOBEC-high bladder cancer cell lines with IFNγ." (PMID 29435122, 2018). "Similar APOBEC3B-mediated cell cycle progression has been observed in bladder cancer." (PMID 36978147, 2023). "The difference in antigenicity may ultimately result in tumor immunity in APOBEC3B-expressing bladder cancer." (PMID 33925044, 2021). "In addition, only APOBEC3B of the APOBEC family showed a significantly higher mRNA expression in bladder cancer than in normal tissue (p < 0.001)." (PMID 33925044, 2021).
bladder cancer (continued). "Expression of APOBEC3A and APOBEC3B correlates with overall mutation load in bladder cancer, regardless of molecular subtype." (PMID 29435122, 2018). "Regulation of APOBEC enzymes remains unclear, but expression of APOBEC3A and APOBEC3B can be induced in bladder cancer cell lines by the DNA-damaging agent bleomycin, as well as by an interferon response." (PMID 29435122, 2018). "Therefore, we thought that increased APOBEC3B activity may accelerate the production of various neoantigens in bladder cancer cells." (PMID 33925044, 2021). "Additionally, our meta-analysis revealed the lack of the association of the APOBEC3B deletion with ovarian cancer [OR(95%CI)=1.070(0.558-2.052), p=0.839] and opposite association (protective effect) of the deletion with bladder cancer [OR(95%CI)=0.834(0.734-0.948), p=0.005]." (PMID 29100317, 2017). "While the roles of APOBEC3A and APOBEC3B in bladder cancer have not been functionally explored, transgenic overexpression of APOBEC3G in a BBN-induced carcinogen mouse model of bladder cancer has documented that APOBEC3G can shorten survival as well as drive genomic instability." (PMID 41390483, 2025). "However, the clinical benefit of APOBEC3s in bladder cancer could be limited to later-stage disease since higher APOBEC3B expression may contribute to the progression from non-muscle-invasive to muscle-invasive disease." (PMID 36978147, 2023).
lung carcinoma (16 papers, 2014 to 2024). "In lung cancer, T cell-mediated immune activation was linked with high APOBEC3B expression or high APOBEC3-induced mutation loads." (PMID 36978147, 2023). "Here we set outto develop mouse models of mutant KRAS-driven lung cancer with an elevated tumormutational burden by expressing the human DNA cytosine deaminase, APOBEC3B, tomimic the mutational signature seen in human lung cancer." (PMID 35930804, 2022). "The enrichment of immune signature in both NSCLC patient samples and lung cancer cell lines implicates a cancer cell intrinsic mechanism for the association between APOBEC3B and immune response gene expression." (PMID 29695832, 2018). "The GAs of SWI/SNF complex may promote liver-specific metastasis by upregulating ALDH1A1 and APOBEC3B expression, providing novel insights into the molecular mechanisms underlying lung cancer liver metastasis." (PMID 37989338, 2023). "A recent study showed causal relationship between APOBEC3B induction and DNA replication stress and CIN in early breast and lung cancer evolution." (PMID 35817785, 2022). "Due to the critical role of APOBEC3B in lung cancer progression and prognosis, we investigated the functional correlation of APOBEC3B expression in both NSCLC patient samples and lung cancer cell lines." (PMID 29695832, 2018). "APOBEC3B expression was reported to be upregulated in lung cancer, and this is independently verified in NSCLC with TCGA datasets." (PMID 29695832, 2018). "And this positive association between APOBEC3B and PD-L1 has been confirmed in different NSCLC databases GSE72094, and also lung cancer cells lines Cancer Cell Line Encyclopedia (CCLE) database." (PMID 29695832, 2018). "Other reports had indicated APOBEC3B was up-regulated in many types of tumor tissues, including ovarian, breast and lung carcinomas." (PMID 27310677, 2016). "The APOBEC3B/β-actin mRNA levels were significantly higher in the lung cancer (24.780±42.625) when compared to the adjacent normal lung (4.176±7.770) tissues (P<0.0001)." (PMID 24748981, 2014). "The results showed that APOBEC3B/β-actin mRNA levels were significantly higher in lung cancer (1,598.481±6,465.781) when compared to adjacent normal lung tissues (2,116.639±8,337.331, P=0.5453)." (PMID 24748981, 2014). "This study highlights the complex and context-dependent role of APOBEC3B in lung cancer." (PMID 38049664, 2024). "Indeed, expressionof APOBEC3B in an EGFRL858R-driven model of lung cancer has also beenshown to be detrimental to tumour initiation." (PMID 35930804, 2022). "High APOBEC3B expression has been associated with poor response to Raf inhibitors in glioma, and certain APOBEC3-induced mutations may predict resistance to Raf inhibitors and EGFR inhibitors in multiple myeloma and lung cancer, respectively." (PMID 36978147, 2023). "To summarise, as with the KP model, APOBEC3B expression failed to induceimmunogenicity in carcinogen-induced models of lung cancer." (PMID 35930804, 2022).
hepatocellular carcinoma (15 papers, 2014 to 2025). A malignant tumor that arises from hepatocytes. "Evidence has shown that APOBEC3B expression is upregulated by inflammatory factors and plays an important role in the genesis and progression of virus-associated cancers, such as hepatocellular carcinoma." (PMID 36249021, 2022). "Additionally, the variant rs2267401 has been shown to increase gallbladder cancer and hepatocellular carcinoma risk, likely by increased APOBEC3B expression that arises through heightened promoter activity and IL-6 response." (PMID 36978147, 2023). "APOBEC3B specifically plays a pivotal role in HBV-related hepatocellular carcinoma progression through its dual functionality." (PMID 40909950, 2025). "For example, the NF-κB target gene IL-6 has been shown to induce APOBEC3B expression in hepatocellular carcinoma via JAK/STAT signaling." (PMID 36978147, 2023). "Exemplifying the importance of these pathways, a study of hepatocellular carcinoma found that overexpression of catalytically inactive APOBEC3B increased cell proliferation, cell migration, and cell invasion in vitro." (PMID 36978147, 2023). "Our group has reported that MSL2 and HULC maintain HBV cccDNA minichromosome stability through the degradation of APOBEC3B in hepatoma cells." (PMID 34931766, 2021). "MiRNA-539 targets the 3’UTR of DNA cytidine deaminase APOBEC3B mRNA to down-regulate the APOBEC3B in hepatoma cells." (PMID 34456908, 2021). "Mutation signature analysis found the presence of signatures other than those induced by APOBEC3B in patient samples of hepatocellular carcinoma." (PMID 29642934, 2018). "Deletion of APOBEC3B attenuated HBV clearance, and resulted in HBV infection and increased risk for developing hepatocellular carcinoma." (PMID 25502777, 2014). "Importantly, it has been reported that there is a positive feedback loop in the presence of chemotaxis between IL-6 and APOBEC3B in hepatoma cells, i.e., APOBEC3B promotes IL-6 to recruit MDSCs and TAMs to promote the development of liver cancer." (PMID 36203448, 2022). "Although the mutation signals found in liver cancer do not appear to affect genomic DNA, there may be other roles of the nuclear-localized APOBEC3B cytidine deaminase in hepatocellular carcinoma cells, thus requiring additional exploration." (PMID 36203448, 2022). "However, the potential role of APOBEC3B in mutagenesis in hepatocellular carcinoma has been controversial, with some studies reporting its tumor-inducing roles and others suggesting that it may play a role in tumor suppression." (PMID 29642934, 2018). "In HBV-related hepatocellular carcinoma, lncRNA activates HBV through regulating HBx/STAT3/miR-539/APOBEC3B axis, thereby promoting the progression of HBV-related hepatocellular carcinoma." (PMID 34104647, 2021).
cervical cancer (13 papers, 2014 to 2023). A primary or metastatic malignant neoplasm involving the cervix. "In conclusion, we found that high APOBEC3B expression was associated with HPV18 infection in women with cervical cancer." (PMID 36560657, 2022). "As expected, HPV18+ samples continued to exhibit significantly increased levels of APOBEC3B expression compared to that group (p = 0.027), suggesting that HPV18 is associated with a differential upregulation of APOBEC3B in human cervical cancer samples." (PMID 36560657, 2022). "All these findings suggest that APOBEC3B was an important regulator of apoptosis in cervical cancer cells and was associated with the malignant phenotype of cervical cancer cells." (PMID 36249021, 2022). "In the genome of cervical cancer patients, APOBEC3B protein over-expression was correlated with the enrichment of APOBEC3B mutation signature." (PMID 29853799, 2018). "Such a link with progression may also be relevant for other cancer types in which APOBEC3B is implicated in generating mutational diversity, such as bladder, lung, head and neck, and cervical cancer; however, this remains to be explored." (PMID 25123150, 2014). "For example, increased expression of APOBEC3B was observed in high- and low-grade cervical lesions when compared to normal cytology, and its enhanced expression was directly associated with the mutational burden in cervical cancer tissues from affected subjects." (PMID 36560657, 2022). "In this study, we describe that APOBEC3B expression is differentially upregulated in human cervical cancer depending on the infecting HPV type." (PMID 36560657, 2022). "In order to investigate the APOBEC3B expression levels in cervical cancer samples, we compared them among distinct HPV type groups." (PMID 36560657, 2022). "The current study aimed to investigate the expression pattern of APOBEC3B (A3B) in cervical cancers and the possible molecular mechanisms of APOBEC3B on the cell cycle as well as HPV oncogenes in cervical cancer." (PMID 36249021, 2022). "Cervical cancer cases in TCGA were divided into two groups based on the high and low expression of APOBEC3B following previous methods." (PMID 36249021, 2022). "HPV infection in HNSC and cervical cancers increased the expression level of APOBEC3B through the viral oncoprotein E6." (PMID 32775421, 2020). "APOBEC3B expression in cervical cancer is associated with HPV-18 infection 10 and is often associated with cell proliferation, migration, and cell cycle progression in cervical cancers, except for gastric-type cervical adenocarcinoma 11-13." (PMID 38021159, 2023). "In cervical cancers, APOBEC3B expression was strongly positive compared with the normal cervix." (PMID 36249021, 2022). "In summary, all results showed that APOBEC3B is markedly elevated in cervical cancer tissues." (PMID 36249021, 2022). "It is suggested that APOBEC3B may play an important role in cancer progression; therefore, we observed whether APOBEC3B promoted cell viability of human cervical cancer cells." (PMID 36249021, 2022). "Cervical cancer cases in GSE26511 were divided into two groups based on the high and low expression of APOBEC3B." (PMID 36249021, 2022). "We found that the LOXL2-interference resulted in an increase in APOBEC3A, APOBEC3B, APOBEC3D, and APOBEC3G protein levels in the cervical cancer cells." (PMID 32211324, 2020). "We further found that APOBEC3B expression was higher in HPV16-positive cervical cancers than in HPV16-positive nonmalignant tissues and HPV-negative histologically normal controls in GSE67522." (PMID 36249021, 2022). "Therefore, we also integrated the APOBEC family (APOBEC1 APOBEC3A, APOBEC3B, APOBEC3C, APOBEC3D, APOBEC3F, APOBEC3G, and APOBEC3H) mRNA expression of 176 core-set cervical carcinoma samples for multiplatform integrative analyses." (PMID 32211324, 2020).
cervical cancer (continued). "Moreover, APOBEC3B was also highly expressed in cervical cancers than in high-grade squamous intraepithelial lesions and normal controls in GSE7803." (PMID 36249021, 2022).
ovarian carcinoma (13 papers, 2014 to 2025). A malignant neoplasm originating from the surface ovarian epithelium. "DNA cytosine deaminase APOBEC3B was recognized recently as a cause of DNA mutagenesis and DNA damage in head/neck, breast, lung, cervix, bladder, and ovary cancer." (PMID 36832196, 2023). "In fact, APOBEC3B exhibited an upregulation pattern in breast and ovarian cancer cell lines, demonstrating a consistent association between this cytidine deaminase activity and neoplasia." (PMID 36560657, 2022). "In consistent with previous studies, our multivariate results showed that higher expression of APOBEC3B was independently associated with worse survival of ovarian cancer patients." (PMID 29853799, 2018). "In conclusion, our study showed that over-expression of APOBEC3B is associated with the development and prognosis of ovarian cancer patients, possibly through influencing viability of ovarian cancer." (PMID 29853799, 2018). "Univariate analysis result showed that histological subtype, FIGO stage, intravascular tumor thrombus, CA125 and APOBEC3B expression were associated with overall survival and disease-free survival of ovarian cancer patients." (PMID 29853799, 2018). "The aim of our study was to extend the current knowledge of the structure of the APOBEC3B deletion, its influence on the expression of the affected genes, and its association with breast and ovarian cancer predisposition in the European population." (PMID 29100317, 2017). "A recent study showed that APOBEC3B overexpression in ovarian cancer correlated with elevated levels of transversion mutations; however, the clinical relevance of these findings still needs to be demonstrated including the potential prognostic relevance." (PMID 27527602, 2016). "However, studies on ovarian cancer and myeloma have shown that APOBEC3B expression is associated with poor prognosis." (PMID 35903294, 2022). "Furthermore, knockdown of APOBEC3B expression in ovarian cancer cells caused an decrease in cell line viability." (PMID 29853799, 2018). "The current study aimed to evaluate the predictive value of APOBEC3B in ovarian cancer prognosis, and to explore the oncogenic role of APOBEC3B in ovarian cancer." (PMID 29853799, 2018). "APOBEC3B siRNA caused a dramatic decrease in APOBEC3B expression in human A2780 and HO-8910PM ovarian cancer cells and knocking-down of APOBEC3B resulted in a modest decrease in cell viability." (PMID 29853799, 2018). "Our immunohistochemistry results also showed that APOBEC3B has a higher ratio of cytoplasmic localization in ovarian cancer tissues." (PMID 29853799, 2018). "Another study showed that APOBEC3B overly expressed in the majority of ovarian cancer cell lines and high-grade primary ovarian cancers." (PMID 29853799, 2018). "The current study aimed to evaluate the predictive value of APOBEC3B in ovarian cancer clinical outcome, and to explore possible molecular mechanisms contributing to ovarian cancer progression." (PMID 29853799, 2018). "The expression of APOBEC3B in biopsy tissue specimens from 88 ovarian cancer patients was examined using immunohistochemistry." (PMID 29853799, 2018). "The resulting two main clusters for ovarian cancer cell lines accentuate the expression differences for APOBEC3B, APOBEC3C, and APOBEC3G as well as of ID2 and ID3." (PMID 27527602, 2016). "APOBEC3B is furthermore elevated in lung cancer, ovarian carcinoma, diverse ovarian cancer cell lines and high grade primary ovarian cancers." (PMID 26097867, 2015). "APOBEC3B was overexpressed in a majority of ovarian cancer cell lines and high grade primary ovarian cancers." (PMID 25502777, 2014). "However, upregulation of APOBEC3B in the head/neck, breast, lung, cervix, bladder, and ovary cancer results in raised levels of Cytosine-to-Uracil deamination cases." (PMID 36832196, 2023). "In addition, APOBEC3B knock down in ovarian cancer cells and glioma results in decreased cell viability and proliferation." (PMID 32934779, 2020).